DIPK2A (divergent protein kinase domain 2A)
Description:
May play a role in cardiomyocyte proliferation through paracrine signaling and activation of the PPI3K-AKT-CDK7 signaling cascade.
Synonyms: GoPro49; HASF; C3orf58; DIA1; MGC33365
Tractability: Antibody: UniProt places it where antibodies can reach, with medium confidence; UniProt predicts a signal peptide or a membrane-spanning region; its Gene Ontology location is reachable by antibodies, with medium confidence. PROTAC: ubiquitination databases record sites on it.
Gene: Protein-coding gene on chromosome 3 (143,971,823 to 144,048,719, forward strand). Ensembl gene ENSG00000181744.
Subcellular location: Cytoplasmic vesicle, COPI-coated vesicle; Golgi apparatus; Secreted
Gene Ontology:
Biological process: cardiac muscle cell proliferation; negative regulation of smooth muscle cell apoptotic process; positive regulation of protein kinase C activity; regulation of phosphatidylinositol 3-kinase/protein kinase B signal transduction
Cellular component: COPI vesicle coat; extracellular region; Golgi membrane; COPI-coated vesicle; Golgi apparatus
Genetic constraint (gnomAD): Loss-of-function variants: 25 observed, 34.79 expected, observed/expected ratio (o/e) 0.72, 90% interval 0.52 to 1. The synonymous counts are far from expectation, so gnomAD's model fits this gene poorly and the ratio says little. Missense variants: 528 observed, 530.85 expected, observed/expected ratio (o/e) 0.99, 90% interval 0.93 to 1.07. Synonymous variants: 298 observed, 222.32 expected, observed/expected ratio (o/e) 1.34, 90% interval 1.22 to 1.48.
Homologues: Orthologues: chimpanzee DIPK2A (99% identical), dog DIPK2A (99% identical), macaque DIPK2A (99% identical), pig DIPK2A (99% identical), mouse Dipk2a (98% identical), guinea pig DIPK2A (90% identical), tropical clawed frog dipk2a (88% identical), zebrafish dipk2ab (82% identical), zebrafish dipk2aa (79% identical), rabbit DIPK2A (63% identical), rat Dipk2a (43% identical), Drosophila melanogaster CG11170 (17% identical). Paralogues in human: DIPK2B (30% identical).
Diseases named in the same sentence as DIPK2A in open-access papers:
DIPK2A is named in the same sentence as 8 diseases in open-access papers, as found by Europe PMC text mining. Sharing a sentence is not in itself a finding about the gene and the disease. The quoted sentences say what the papers report.
autism (3 papers, 2011 to 2022). Persistent deficits in social interaction and communication and interaction as well as a markedly restricted repertoire of activity and interest as well as repetitive patterns of behavior. "The ctSPs are eQTL for DIPK2A (C3orf58), which encodes for a protein kinase and has been associated with autism and other neurological disorders." (PMID 35606693, 2022).
periodontal disease (1 paper, 2025). "The most robust associations found for each phenotype are as follows: DMFT with rs79198416 (near CDC73/KCNT2; p = 7.57E-07), periodontal disease with rs73870587 (DIPK2A, p = 7.38E-08); CIMT with rs113152669 (LRP1Bp = 4.07E-07), and CAC with rs76676138 (CNTNAP2; p = 2.47E-19)." (PMID 41006734, 2025).
cancer (1 paper, 2019). A tumor composed of atypical neoplastic, often pleomorphic cells that invade other tissues. "An association of DIPK2A with cancer has not been reported so far." (PMID 31888295, 2019).
DIPK2A also shares sentences with these, for which no sentence is quoted: neurological disorders (2 papers); acral lentiginous melanoma (1); autism spectrum disorder (1); coronary artery disease (1); myocardial infarction (1).